TTLL2 (tubulin tyrosine ligase like 2)
Description:
Probable tubulin polyglutamylase that generates side chains of glutamate on the gamma-carboxyl group of specific glutamate residues within the C-terminal tail of target proteins (By similarity). Similar to TTLL1, may acquire enzymatic activity only in complex with other proteins as it is most likely lacking domains important for autonomous activity (By similarity). Probably involved in the side-chain initiation step of the polyglutamylation reaction rather than the elongation step (By similarity).
Synonyms: C6orf104; NYD-TSPG; dJ366N23.3
Tractability: No criterion of Open Targets' tractability assessment is met for any kind of drug.
Gene: Protein-coding gene on chromosome 6 (167,325,071 to 167,359,503, forward strand). Ensembl gene ENSG00000120440.
Subcellular location (Human Protein Atlas): Nuclear membrane; Nucleoli
Pathways (Reactome):
Metabolism of proteins: Carboxyterminal post-translational modifications of tubulin
Gene Ontology:
Molecular function: protein binding; tubulin binding; tubulin-glutamic acid ligase activity
Biological process: microtubule cytoskeleton organization
Cellular component: ciliary basal body
Genetic constraint (gnomAD): Loss-of-function variants: 12 observed, 9.72 expected, observed/expected ratio (o/e) 1.23, 90% interval 0.78 to 1.84. That is too few expected variants to judge how well the gene tolerates losing a copy. Missense variants: 733 observed, 768.19 expected, observed/expected ratio (o/e) 0.95, 90% interval 0.9 to 1.01. Synonymous variants: 284 observed, 290.64 expected, observed/expected ratio (o/e) 0.98, 90% interval 0.89 to 1.08.
Homologues: Orthologues: chimpanzee TTLL2 (98% identical), macaque TTLL2 (93% identical), dog TTLL2 (64% identical), mouse Ttll2 (60% identical), rat Ttll2 (59% identical), tropical clawed frog ttll2 (42% identical), zebrafish ttll2 (38% identical). Paralogues in human: TTLL4 (25% identical), TTLL13 (23% identical), TTLL6 (23% identical), TTLL7 (23% identical), TTLL1 (20% identical), TTLL11 (19% identical), TTLL9 (19% identical), TTLL8 (16% identical), TTLL10 (16% identical), TTLL3 (16% identical), TTLL12 (13% identical), KPRP (7% identical).
Diseases named in the same sentence as TTLL2 in open-access papers:
TTLL2 is named in the same sentence as 4 diseases in open-access papers, as found by Europe PMC text mining. Sharing a sentence is not in itself a finding about the gene and the disease. The quoted sentences say what the papers report.
Alzheimer disease (1 paper, 2019). A progressive, neurodegenerative disease characterized by loss of function and death of nerve cells in several areas of the brain leading to loss of cognitive function such as memory and language. "Finally, in the broader context of traits potentially related to cognition, we find an enrichment of HHMCs in genes associated to “Alzheimer’s disease (cognitive decline)” and “Cognitive decline (age-related)”, with seven associated genes (COX7B2, BCAS3, DMXL1, LIPC, PLEKHG1, TTLL2 and VIT)." (PMID 31186485, 2019).
cancer (1 paper, 2021). A tumor composed of atypical neoplastic, often pleomorphic cells that invade other tissues. "Controlling the false discovery rate at 5%, ECAR selected six genes CHRM3, CTCFL, KCNE2, MLANA, MSMP, TTLL2, many of which have been reported to be associated with lung function or cancer." (PMID 34857823, 2021).
TTLL2 also shares sentences with these, for which no sentence is quoted: cognitive decline (1 paper); tumor (1).